C8B (complement C8 beta chain)
Description:
Component of the membrane attack complex (MAC), a multiprotein complex activated by the complement cascade, which inserts into a target cell membrane and forms a pore, leading to target cell membrane rupture and cell lysis. The MAC is initiated by proteolytic cleavage of C5 into complement C5b in response to the classical, alternative, lectin and GZMK complement pathways. The complement pathways consist in a cascade of proteins that leads to phagocytosis and breakdown of pathogens and signaling that strengthens the adaptive immune system. C8B, together with C8A and C8G, inserts into the target membrane, but does not form pores by itself. During MAC assembly, associates with C5b, C6 and C7 to form the C5b8 intermediate complex that inserts into the target membrane and traverses the bilayer increasing membrane rigidity.
Synonyms: C82
Tractability: Antibody: UniProt places it where antibodies can reach, with high confidence; its Gene Ontology location is reachable by antibodies, with high confidence; UniProt predicts a signal peptide or a membrane-spanning region.
Gene: Protein-coding gene on chromosome 1 (56,929,099 to 56,974,383, reverse strand). Ensembl gene ENSG00000021852.
Subcellular location: Secreted; Target cell membrane
Pathways (Reactome):
Immune System: Regulation of Complement cascade; Terminal pathway of complement
Gene Ontology:
Molecular function: wide pore channel activity; protein-containing complex binding
Biological process: complement activation; complement activation, GZMK pathway; killing of cells of another organism; immune response; positive regulation of immune response; transmembrane transport
Cellular component: extracellular exosome; extracellular region; extracellular vesicle; membrane attack complex; other organism cell membrane; membrane; plasma membrane
Genetic constraint (gnomAD): Loss-of-function variants: 65 observed, 67.72 expected, observed/expected ratio (o/e) 0.96, 90% interval 0.79 to 1.18. The upper end of that interval is the gene's LOEUF score, 1.18, which puts it in group 5 of 6, group 1 being the genes least tolerant of losing a copy. Missense variants: 750 observed, 733.8 expected, observed/expected ratio (o/e) 1.02, 90% interval 0.96 to 1.09. Synonymous variants: 272 observed, 262.67 expected, observed/expected ratio (o/e) 1.04, 90% interval 0.94 to 1.14.
Homologues: Orthologues: chimpanzee C8B (99% identical), macaque C8B (95% identical), dog C8B (85% identical), pig C8B (84% identical), guinea pig C8B (80% identical), rat C8b (79% identical), rabbit C8B (77% identical), mouse C8b (75% identical), tropical clawed frog c8b (57% identical), zebrafish c8b (45% identical). Paralogues in human: C8A (31% identical), C6 (28% identical), C7 (27% identical), C9 (24% identical), CSMD2 (16% identical), PAPPA (16% identical), CSMD1 (16% identical), PAPPA2 (16% identical), CSMD3 (15% identical), PRF1 (15% identical), CFH (14% identical), SVEP1 (13% identical), and 27 more.
Diseases named in the same sentence as C8B in open-access papers:
C8B is named in the same sentence as 22 diseases in open-access papers, as found by Europe PMC text mining. Sharing a sentence is not in itself a finding about the gene and the disease. The quoted sentences say what the papers report.
COVID-19 (3 papers, 2022). A disease caused by infection with severe acute respiratory syndrome coronavirus 2. "Interestingly, when comparing AH in the RO group transplanted with GTKO porcine cornea with that in the survival group, six proteins (C3, C5, C7, C9, C8B, and C8G) were enriched in the “Coronavirus disease - COVID-19” KEGG pathway (data not shown)." (PMID 35401527, 2022).
hepatocellular carcinoma (2 papers, 2025 to 2026). A malignant tumor that arises from hepatocytes. "The C8B gene encodes the beta subunit of complement complex 8, which has recently been found to have predictive potential in hepatocellular carcinoma (HCC) development." (PMID 40313868, 2025).
bipolar disorder (1 paper, 2022). A disorder of the brain that causes unusual shifts in mood, energy, activity levels and the ability to carry out day-to-day tasks. "C8B is a compound that forms a component of the membrane attack complex, and elevated levels have been associated with the development of psychiatric disorders in pediatric cases and adult cases of schizophrenia and major depression disorder/bipolar disorder." (PMID 36670596, 2022).
complement deficiencies (1 paper, 2015). "The association between C8B rs12085435 and risk of meningococcal disease in our study is in keeping with the effect of inherited terminal complement deficiencies on susceptibility to meningococcal disease." (PMID 25798599, 2015).
fibroepithelial polyp (1 paper, 2025). A polypoid lesion composed of fibrous tissue and epithelium. "The other mutations found in our case (DNMT3A, C8B, TET2, SDHA, ARID1B, NOTCH1, OR5L1, and KDM6A) do not have a known association with the formation of fibroepithelial polyps." (PMID 40936011, 2025).
meningococcal disease (1 paper, 2015). "Independent replication will be key to establishing whether C8B is a second complement gene associated with meningococcal disease risk." (PMID 25798599, 2015).
Rolandic epilepsy (1 paper, 2024). "The overexpression of C8B was found in the plasma of patients with Rolandic epilepsy." (PMID 39063177, 2024).
tumor (5 papers, 2022 to 2025). "The results showed that ADH4 and C8B expression levels were downregulated in tumor tissues compared with non-tumor tissues." (PMID 38654290, 2024). "The result showed that the lower mRNA expressions of C3, C5, CFB, and CLU were correlated with more advanced cancer stage, while the lower mRNA expressions of C1S, C8B, CFI, MBL2, and C4BPA were correlated with higher tumor grade in HCC patients." (PMID 34813686, 2022). "In addition, the mRNA expressions of C1S, C8B, MBL2, CFI, and C4BPA were correlated with tumor grade and prognosis in HCC patients." (PMID 34813686, 2022). "However, while our study found C8B upregulation in BLCA, the meta-analysis reported downregulation of C8B and other complement regulators in BLCA, possibly due to sample differences, tumor heterogeneity, or variations between transcriptomic and proteomic analyses." (PMID 40283026, 2025).
cancer (2 papers, 2022 to 2025). A tumor composed of atypical neoplastic, often pleomorphic cells that invade other tissues. "C8B is a component of the membrane attack complex (MAC), which plays complex roles in cancer." (PMID 40283026, 2025).
C8B also shares sentences with these, for which no sentence is quoted: infection (3 papers); Allergy (1); liver fibrosis (1); lung carcinoma (1); major depression disorder (1); Mycobacterium infection (1); periodontitis (1); psychiatric disorder (1); renal fibrosis (1); schizophrenia (1); Sepsis (1); staphylococcus aureus infection (1); thyrotoxicosis (1).